LPL (lipoprotein lipase)
Diseases named in the same sentence as LPL in open-access papers (continued):
Sharing a sentence is not in itself a finding about the gene and the disease.
hypertriglyceridemia (continued). "Not only SNAT2 but also Rheb expression, which activates the mTORC1/S6K pathway in the liver, induced hypertriglyceridemia, especially in postprandial states, via decreased TG hydrolysis mainly owing to adipose LPL downregulation." (PMID 26268630, 2015). "Hypertriglyceridemia was a reflection of IR and decreased adipose tissue lipoprotein lipase activity." (PMID 26413164, 2015). "Under this condition, Rheb-induced hypertriglyceridemia was markedly improved by LPL expression to an extent similar to that observed in ZZ mice." (PMID 26268630, 2015). "Familial chylomicronemia syndrome (FCS) is a rare lipid disease caused by complete lipoprotein lipase (LPL) deficiency resulting in fasting chylomicronemia and severe hypertriglyceridemia." (PMID 25889044, 2015). "LPL activities obtained from 71 patients with documented history of major hypertriglyceridemia showed a trimodal distribution." (PMID 24788417, 2014). "As prolonged hypertriglyceridemia in lobster indicates a decreased ability of tissues to remove plasma triacylglycerol, the activity of tissue lipoprotein lipase is worthy to be studied further." (PMID 25268641, 2014). "Compared to patient with low LPL activity (<10 μmol/l/min), the 47 genotyped (TVHTG) patients with LPL activity over 10 μmol/l/min had milder hypertriglyceridemia (8.9±8.0 mmol/l p<0.01)." (PMID 24788417, 2014). "Dysfunction of LPL induces pathophysiological lipid-related disorders, including hyperlipidemia, dyslipidemia, and hypertriglyceridemia." (PMID 25493549, 2014). "Increased production of triglyceride-rich proteins and the diminished clearance by lipoprotein lipase result in hypertriglyceridemia, which is typically observed in diabetes." (PMID 24563867, 2014). "In fact, ANGPTL4 is a potent irreversible inhibitor of lipoprotein lipase (LPL) activity, which leads to hypertriglyceridemia." (PMID 23947536, 2013). "In this regard, it has been demonstrated that LPL overexpression prevents the development of diet-induced hypertriglyceridemia and hypercholesterolemia and decreases VLDL and LDL fractions levels." (PMID 24367387, 2013). "Overexpression of the human LPL remarkably ameliorates hypertriglyceridemia in transgenic Watanabe heritable hyperlipidemic rabbits." (PMID 24086538, 2013). "We also show that VAAST 2.0 outperforms KBAC, WSS, SKAT, and variable threshold (VT) using published case-control datasets for Crohn disease (NOD2), hypertriglyceridemia (LPL), and breast cancer (CHEK2)." (PMID 23836555, 2013). "Another study in a South Indian population identified variants in the LPL gene to be associated with HDL-cholesterol and hypertriglyceridemia." (PMID 23150898, 2012). "These hamsters, in contrast to other rodents, have low lipoprotein lipase (LPL) activity, develop hypertriglyceridemia, and hypercholesterolemia and are particularly sensitive to BOP carcinogenesis." (PMID 23049538, 2012). "ApoCIII is an 8.8 kDa polypeptide synthesized by the liver and playing an important role in controlling catabolism of triglyceride-rich lipoproteins by inhibiting the activity of lipoprotein lipase thereby inducing hypertriglyceridemia." (PMID 19196457, 2009). "Patients with severe hypertriglyceridemia (sHTG) have variable lipoprotein lipase (LPL) activity levels that may influence therapeutic response." (PMID 41831525, 2026). "Thus, there is a great need to understand the tissue-specific regulation and contribution of LPL to hypertriglyceridemia and atherosclerosis." (PMID 40100923, 2025). "In the presence of insulin resistance, the increased flow of free fatty acids to the liver triggers hepatic very low-density lipoprotein (VLDL) production, while reduced lipoprotein lipase activity slows the clearance of triglyceride-rich lipoproteins, leading to hypertriglyceridemia." (PMID 41426805, 2025).
hypertriglyceridemia (continued). "Additionally, hypertriglyceridemia has been shown to reduce the expression of LPL in muscle and adipose tissues, impairing the enzyme’s ability to bind to the lipoprotein surface, disrupting lipolysis and facilitating the transport of TRL back to the liver." (PMID 40298782, 2025). "Mutations in genes encoding lipoprotein lipase, apolipoprotein C-II (APOC2), apolipoprotein A-V (APOA5), and other enzymes involved in lipid metabolism have been associated with severe hypertriglyceridemia, particularly when triggered by medications or metabolic stress." (PMID 40862038, 2025). "It is likely that the type of LPL variant influences the severity of hypertriglyceridemia: a null allele without any residual activity is likely to have a more severe phenotype compared to a missense LPL pathogenic variant with 25% residual activity." (PMID 40004987, 2025). "Hypertriglyceridemia observed in T1DM patients may be attributed to increased VLDL production secondary to relative insulin deficiency and decreased lipoprotein lipase activity in patients inadequately treated with insulin." (PMID 40076685, 2025). "For a considerable period, it has been undecided whether the hypertriglyceridemia following diabetes was an outcome of augmented synthesis of VLDL-TG from the liver or a product of reduced clearance of lipoprotein-TG by LPL." (PMID 39081272, 2024). "Hypertriglyceridemia is associated with the activation of LPL, which hydrolyzes plasma TGs into nonesterified fatty acids." (PMID 38973609, 2024). "Further investigation is needed to determine whether LPL is involved in MIF-regulated AAP-induced hypertriglyceridemia in patients with SZ." (PMID 38802393, 2024). "Thus, both alteration of LPL and HSL activities explored in the previous section can become direct causes of hypertriglyceridemia." (PMID 38892018, 2024). "Furthermore, increased circulating MIF levels play a role in inducing hypertriglyceridemia by downregulating lipoprotein lipase (LPL) in adipose tissue." (PMID 38802393, 2024). "Patients with T2D have mild hypertriglyceridemia often due overproduction of TG‐rich lipoproteins in the liver, associated with decreased high‐density lipoprotein (HDL) cholesterol level as a result of defective LPL catabolism of TG‐rich lipoproteins." (PMID 39500546, 2024). "Injection of P407 into mice produces severe hypertriglyceridemia (HTG) because it directly inhibits lipoprotein lipase (LPL)’s enzyme activity can be used to investigate the effects of HTG on atherosclerosis and the potential role of monocytes in these processes." (PMID 38066464, 2023). "Besides, it was reported in the previous study that ANGPTL4 can regulate the activity of lipoprotein lipase activity and hypertriglyceridemia." (PMID 37821811, 2023). "Given the severity of the hypertriglyceridemia in Apoa5–/– mice, we began with a simple hypothesis: that APOA5 deficiency reduces the amounts of LPL within capillaries." (PMID 37824203, 2023). "Currently, such dietary modifications are not the standard of care for LPL deficiency or hypertriglyceridemia." (PMID 37630727, 2023). "However, to the best of our knowledge, the treatment of LPL patients with an MCT-enriched diet has only been reported in one single-center retrospective study of fifteen patients with hypertriglyceridemia above 11.3 mmol/L." (PMID 37630727, 2023). "The clinical presentation of LPL can overlap with other conditions characterized by hypertriglyceridemia, such as uncontrolled diabetes mellitus, hypothyroidism, and specific medications like thiazide diuretics and estrogen-containing contraceptives, as well as excessive alcohol consumption." (PMID 37630727, 2023).
hypertriglyceridemia (continued). "In addition, overexpression of ANGPTL4 decreased LPL activity, increased plasma TG levels, and triggered hypertriglyceridemia in a fasting mouse model, but the effect of ANGPTL4 was diminished during a long-term high-fat feeding program." (PMID 36837768, 2023). "However, the activity of hepatic lipoprotein lipase in the liver will decrease due to the effects of circulating LIGHT, causing lipid accumulation and hypertriglyceridemia." (PMID 37108160, 2023). "Preterm infants are at a higher risk for hypertriglyceridemia than term neonates due to the lack of adequate muscle and fat reserves, which accounts for a reduced hydrolytic capacity of the lipoprotein lipase enzyme." (PMID 37138099, 2023). "The mice exhibited hypertriglyceridemia after inhibiting LPL activity." (PMID 37233656, 2023). "As severe hypertriglyceridemia is an established risk factor of CVD, it is important to investigate the distribution of LPL/APO CII gene polymorphism in the Kurdish population, as this polymorphism might provide insight into the nature of the disease." (PMID 37954769, 2023). "In addition to LPL, inhibition of hepatic lipase (HL) by P-407 in mice has been suggested to contribute to hypertriglyceridemia." (PMID 36814487, 2023). "However, little is known about the LPL/APO CII gene polymorphism in the Kurdish population, especially among those with severe hypertriglyceridemia." (PMID 37954769, 2023). "Weight loss acquired via caloric restriction, pharmacological measures, or bariatric surgery improves hypertriglyceridaemia via multifaceted approaches including improved insulin resistance, glycaemic control, increase in LPL activity, and reduction in ApoC3 levels." (PMID 37233662, 2023). "The greater tendency of insulin resistance in non-LPL FCS may suggest a contribution of this secondary factor to severe hypertriglyceridaemia or the effect of non-LPL gene products in governing insulin sensitivity." (PMID 37233662, 2023). "Alterations in the LPL gene contribute to severe hypertriglyceridemia." (PMID 35741760, 2022). "Firstly, during infectious state, lipoprotein lipase (LPL)-mediated blood triglyceride clearance decreases, which may induce hypertriglyceridemia." (PMID 36061633, 2022). "APOA5 deficiency leads to hypertriglyceridemia, which may reflect its role in the efficient association of TRL with LPL or GPIHBP1 on endothelial cells, possibly because APOA5 interferes with an inhibitory effect of ANGPTL3/ANGPTL8 on this association." (PMID 34981790, 2022). "Hypertriglyceridemia caused by HFD has been reported to be due to the increased hepatic TG production and VLDL-Ch secretion due to the increased adipocyte hormone-sensitive lipase activity and the decreased lipoprotein lipase activity in muscles." (PMID 35774377, 2022). "For example, some fish oil components have the potential to treat patients with hypertriglyceridemia by inhibiting diacylglycerol acyltransferase, increasing the activity of plasma lipoprotein lipase, decreasing lipogenesis, and inducing β-oxidation processes in the liver." (PMID 36005531, 2022). "Since hypertriglyceridemia (HTG) is a major risk factor for cardiovascular disease (CVD), the leading cause of death worldwide, methods that accurately quantify the hydrolytic activity of LPL in clinical and pre-clinical samples are much needed." (PMID 35911520, 2022). "The consequence is low plasma levels of LPL, and severe hypertriglyceridemia." (PMID 36051701, 2022). "Lastly, cyclosporine induces an increase in apoCIII (endogenous inhibitor of LPL) that could result in hypertriglyceridaemia and an increased concentration of small dense LDL." (PMID 36009482, 2022). "In a normal state, it was reported that insulin activates lipoprotein lipase, which hydrolyzes triglycerides, however, in a diabetic state, the enzyme’s inactivation may result in hypertriglyceridemia." (PMID 35308202, 2022).
hypertriglyceridemia (continued). "Besides LPL, there are other genes involved in primary hypertriglyceridemia phenotypes (most notably, APOC2, APOA5, LMF1, and GPIHBP1)." (PMID 36051701, 2022). "JCL Roundtable: Hypertriglyceridemia due to defects in lipoprotein lipase function." (PMID 33566983, 2021). "Genetic studies revealed that homozygous or biallelic loss-of-function variants in LPL or its partners (GPIHBP1, APOC2, LMF1, APOA5) severely impair the efficiency of triglyceride hydrolysis, causing lifelong severe hypertriglyceridemia—the familial chylomicronemia syndrome." (PMID 34336854, 2021). "In addition, adipose tissue and skeletal muscle contain lipoprotein lipase, which can lead to hypertriglyceridemia." (PMID 35010709, 2021). "It is also highly probable that the observed hypertriglyceridemia was a results of reduced lipoprotein lipase (LPL) activity as a result of insulin decrease in our study (LPL is responsible for the triglyceride-rich lipoprotein hydrolysis and is activated by insulin)." (PMID 35050980, 2021). "In addition, the increased mRNA levels of Apoc3, which is usually downregulated by insulin, reasserts some degree of IR in the liver contributing to hypertriglyceridemia by the diminished TG hydrolysis by the LPL." (PMID 34202724, 2021). "The aim of this study was to evaluate the impact of hypercholesterolemia and hypertriglyceridemia on the efficiency of lipoprotein lipase (LPL)-mediated very-low-density lipoprotein (VLDL)-triglyceride lipolysis and the role of high-density lipoprotein (HDL) in this process." (PMID 33917704, 2021). "No mutation in the major genes involved in severe hypertriglyceridemia (LPL, APOAV, APOCII, LMF1, GPIHBP1) was found." (PMID 35011612, 2021). "Although ApoC-III atherogenicity was primarily attributed to hypertriglyceridemia because of its ability to inhibit endothelial-bound lipoprotein lipase, recent evidence expands this function and reveals ApoC-III’s key role in endothelial activation and arterial inflammation." (PMID 33407555, 2021). "In addition, TNF-α can reduce the activity of lipoprotein lipase and IL-6 increase the uptake of fatty acids to adipose tissue and to the liver, which in turn promotes hypertriglyceridemia." (PMID 32187268, 2020). "According to some studies, hypertriglyceridemia could be the result of the inhibition of lipoprotein lipase (LPL)." (PMID 33008076, 2020). "Thus, we assumed that NDGA, LPL inhibitor-mediated hypertriglyceridemia, hypercholesterolemia, hypoadiponetimia, and hyperglycemia are compensated due to the action of hepatic lipid homeostasis caused by LPL." (PMID 31234537, 2019). "In addition, recent reports have identified the presence of GPIHBP1 antibodies that inhibit the ability of GPIHBP1 to bind and transport LPL in patients with hypertriglyceridemia." (PMID 30947712, 2019). "Conversely, the APOE level in VLDL particles increased with progression of renal dysfunction, which may lead to their delayed metabolism and, in a consequence, to hypertriglyceridemia since APOE inhibits lipoprotein lipase activity." (PMID 30851738, 2019). "Hypertriglyceridemia becomes evident due to the cytokine-inducedinhibition of lipoprotein lipase." (PMID 31635495, 2019). "These patients were found to have increased plasma levels of ANGPTL3 (but not plasma levels of ANGPTL4), suggesting the possibility that hypertriglyceridemia might be the result of ANGPTL3 mediated inhibition of LPL." (PMID 29752428, 2019). "Human subjects with LPL deficiency showed low HDL cholesterol and hypertriglyceridemia." (PMID 31234537, 2019). "The W14X SNP in LPL was first reported in a Japanese woman with hypertriglyceridemia." (PMID 29921298, 2018). "Variants in the lipoprotein lipase (LPL), apolipoprotein C-II (APOC2), apolipoprotein A-V (APOA5), GPIHBP1 and LMF1 genes may cause severe hypertriglyceridemia (HTG), which is now the second-leading aetiology of acute pancreatitis in China." (PMID 29921298, 2018).
hypertriglyceridemia (continued). "Thus, production of LPL by striated muscle reversed hypertriglyceridemia arising from knock out of striated muscle LPL." (PMID 29304082, 2018). "Based on these findings, DNL and decreased lipoprotein lipase-mediated clearance may be a contributing factor to fructose-induced postprandial hypertriglyceridemia." (PMID 28555043, 2017). "LncRNA, liver-specific triglyceride regulator, was recently identified and showed to inhibit apolipoprotein C2 (apoC2) expression through a famesoid X receptor-mediated pathway, whose depletion led to robust lipoprotein lipase activation and hypertriglyceridemia." (PMID 28275212, 2017). "Most of this sialylated protein is secreted from skeletal muscle, heart, and adipose tissue when proteinuria reaches nephrotic range in an attempt to reduce proteinuria through glomerular endothelial binding; it induces also hypertriglyceridemia via inhibition of lipoprotein lipase (LPL)." (PMID 25925039, 2016). "Additionally, ApoCIII is a key contributor to hypertriglyceridemia, primarily due to its inhibitory actions on LPL." (PMID 27444154, 2016). "Excessive production of TG-rich lipoproteins and its low clearance by lipoprotein lipase in diabetic patients may lead to hypertriglyceridemia." (PMID 26909486, 2016). "Also, the zeolite nanoparticles can potentially be used for selectively capture of APOC-III in order to reduce the activation of lipoprotein lipase inhibition during hypertriglyceridemia treatment." (PMID 26616161, 2015). "Thus, hepatic mTORC1/S6K activation induces hypertriglyceridemia involving decreased LPL expression in WAT." (PMID 26268630, 2015). "In the present study, we hypothesized that the difference in the AngII regulation of LPL metabolism in either VAT or SAT may explain the difference in their contributions to hypertriglyceridemia, a component of metabolic syndrome." (PMID 26447765, 2015). "Plasma TG-hydrolysis activity and LPL activity were increased, by almost 15% as compared with LacZ mice, to an extent similar to those in obese DN-S6K mice, resulting in the improvement of obesity-related hypertriglyceridemia." (PMID 26268630, 2015). "Thus, hepatic AA/mTORC1/S6K activation induced hypertriglyceridemia involving adipose LPL downregulation." (PMID 26268630, 2015). "For example, lipoprotein lipase deficient mice have severe hypertriglyceridemia without increased atherosclerosis." (PMID 26694027, 2015). "Reducing plasma TG clearance because of decreased lipoprotein lipase levels may also contribute to fructose-induced hypertriglyceridemia." (PMID 24475021, 2014). "Most of this sialylated protein is secreted from skeletal muscle, heart and adipose tissue when proteinuria reaches nephrotic range in an attempt to reduce proteinuria through glomerular endothelial binding, but also induces hypertriglyceridemia via inhibition of lipoprotein lipase (LPL)." (PMID 24611049, 2014). "A group of 6 TVHTG patients had high LPL activity despite hypertriglyceridemia." (PMID 24788417, 2014). "In this context, a pathological model may be constructed to study LPL dysfunction-induced diseases, such as type 2 diabetes, coronary disease, and hypertriglyceridemia." (PMID 24086538, 2013). "TNF alpha and IL-6 also suppress lipoprotein lipase synthesis in adipose tissue, which may contribute to hypertriglyceridemia and the low HDL-cholesterol concentrations observed in individuals with intra-abdominal obesity." (PMID 23526980, 2013). "In diabetic status, lipoprotein lipase is not activated due to insulin deficiency resulting in hypertriglyceridemia and hypertriglyceridemia." (PMID 24373672, 2013). "Thus, data regarding LPL selective inducers are necessary for determining the relationship between hypertriglyceridemia and intestinal carcinogenesis." (PMID 22028972, 2012). "Interestingly, a study performed in rats suggests that bexarotene-induced hypertriglyceridemia is attributable to inhibition of LPL activity in the muscle." (PMID 23056264, 2012).